FOXC2 (forkhead box C2)
Diseases named in the same sentence as FOXC2 in open-access papers (continued):
Sharing a sentence is not in itself a finding about the gene and the disease.
tumor (continued). "We found that FOXA1 and FOXM1 were significantly positively correlated with tumor purity in patients with BRCA, while FOXC2, FOXO3, FOXP1, and FOXQ1 were significantly negatively correlated with tumor purity in patients with BRCA." (PMID 38608123, 2024). "We observed that TrkB-mediated upregulation of DJ-1 stability activates tumor progression to malignancy by inducing an EMT program via upregulation of EMT-TFs, including Foxc1 and Foxc2, Snail, Goosecoid, Twist-1, and Twist-2." (PMID 37749450, 2023). "For example, in GC patients, YBX1 binds with FOXC2 (Forkhead box protein C2) mRNA, which is m5C-modulated by NSUN2, to enhance its tumor-promoting ability." (PMID 37325635, 2023). "Here, we have shown that VM-proficient tumor cells from breast and SCLC, at least, up-regulate an embryonic endothelial TF FOXC2 to drive VM." (PMID 37499655, 2023). "One study reported that MC-1-F2, a small molecule inhibitor of FOXC2, reverses EMT and inhibits tumor metastasis by degrading FOXC2, blocking its nuclear localization, and inducing calmodulin conversion." (PMID 35965509, 2022). "Some DEGs have been proved to play an important role in regulating tumor cell invasion ability such as WNT7A, VEGFA, EFEMP1, TRPV2, and FOXC2, whose expressions are consistent with the phenotype (see Results)." (PMID 35755807, 2022). "Forkhead box C2 (FOXC2), a critical transcriptional factor that affects EMT, induces tumor angiogenesis and metastasis." (PMID 33937049, 2021). "Zhu KP found that FOXC2 was up‐regulated in OS, and FOXC2 interacted with lncRNA ENST00000563280 and promoted tumour angiogenesis and epithelial‐to‐mesenchymal transition (EMT) in OS." (PMID 32249539, 2020). "HCC patients in the FOXC2-Hi group showed more aggressive clinicopathologic characteristics, including higher serum AFP levels, larger tumor size, more recurrence, lower tumor differentiation, and later clinical stage." (PMID 32508532, 2020). "Thus, FOXC2 may act as a mediator of tumor angiogenesis induced by ZNF750 knockdown in ESCC." (PMID 32341351, 2020). "Frozen tumor tissues and plasma were used to measure PBRM1, BAP1, SET domain-containing 2 (SETD2), KDM5C, FOXC2, CLIP4, AQP1, DDX11, BAIAP2L1, and TMEM38B mRNA levels, and correlation with the Fuhrman grade was investigated." (PMID 32392781, 2020). "Conversely, by focusing on a correlation between high FOXC2 and Cadherin switch, we showed that high expression of FOXC2 in clinical HCC samples is involved in EMT-related tumor aggressiveness." (PMID 29801468, 2018). "Relative expression of PRKCA, FOXC2, and CTNND1 in all tumor samples, using the AgilentG4502A_07_3 array platform, were computed and visualized by a heat map." (PMID 29216867, 2017). "Resveratrol’s anti-tumor effects in A549 xenografts were reduced in Forkhead box protein C2 (FOXC2)-overexpressing A549 xenografts, which suggests that resveratrol possibly induces anti-tumor activity through FOXC2." (PMID 29194365, 2017). "Recent studies suggest that FoxC2 is an EMT inducer and correlates with tumor metastasis and angiogenesis." (PMID 26758745, 2016). "In addition, recent studies demonstrate that haplodeficiency of Foxc2 may result in impaired formation of tumor blood vessels as well as reduced tumor growth, and thereby provide evidence for the association of Foxc2 with the metastasis and angiogenesis of tumors." (PMID 23815774, 2013). "Matrix metalloproteinase (MMP) 2 expression was also diminished in B16 tumors from FoxC2+/– mice, which is consistent with evidence that MMP2 is important for tumor growth and angiogenesis." (PMID 22174714, 2012). "FoxC2 is an important regulator of EMT, a key process that is often activated during tumor progression and metastasis." (PMID 22174714, 2012). "Unlike SNAIL, FOXC2 expression correlated significantly with lymph node involvement (p = 0.048) and tumor type (p = 0.042), indicating its potential as both a biomarker and prognostic indicator of disease severity." (PMID 40781106, 2025).
tumor (continued). "The downregulation of FOXC1, FOXC2, and SOX11 suggests these transcription factors may play a role in maintaining tumour differentiation and regulating metastatic behaviour, warranting further investigation." (PMID 40683913, 2025). "What Folkman did not anticipate was the ability of tumor cells to undergo epithelial-to-endothelial transition driven by co-option of an embryonic endothelial TF FOXC2, creating tumor-derived vasculature that does not depend on canonical angiogenic signals." (PMID 37499655, 2023). "This analysis revealed elevated expression of FOXC2-target genes and endothelial genes in aggressive Basal/Claudin-low tumors only in the human/tumor compartment and not the mouse/stromal compartment." (PMID 37499655, 2023). "A prospective study examining frozen tissue qRT-PCR of AQP1, DDX11, BAIAP2L1, and six previously identified genes (PBRM1, BAP1, SETD2, KDM5C, FOXC2, and CLIP4) showed that expression of DDX11 was a significant factor for predicting tumor aggressiveness based on Fuhrman grade." (PMID 31963294, 2020). "In line with above views, we observed frequent and aberrant FOXC2 expression in HCC tissues and a significant positive correlation between FOXC2 expression and malignant clinicopathology of HCC patients including tumor size, UICC stage and metastasis/recurrence status." (PMID 32508532, 2020). "Additionally, analysis of publicly available clinical PCa tumor data showed metastatic prostate tumors demonstrate a positive correlation between insulin receptor expression and the EMT transcription factor FOXC2." (PMID 31379747, 2019). "Quantitative real-time PCR experiments find that miR-31 has the most notable oncogenic targets AXIN1, which is involved in Wnt signaling pathway and forkhead family transcription factors FOXC2 and FOXP3, and this target gene and the two transcription factors are correlated with tumor stages." (PMID 29513198, 2017). "FOXC2 was previously termed Mesenchyme Forkhead 1 (MFH-1), and recently has been identified as an essential mediator of the epithelial-mesenchymal transition (EMT) process that is mainly activated during tumor metastasis and progression." (PMID 27283491, 2016). "We determined that FOXC2 induces tumor angiogenesis through VEGF-A, but that it is not involved in lymphangiogenesis in OSCCs, results that are somewhat in accord with past reports." (PMID 24647631, 2014). "We then assessed the expression of Prox1 and FOXC2 mRNA in 5 samples of non-tumor oral mucosa, 10 samples of metastasis-negative OSCCs, and 5 samples of metastasis-positive OSCCs." (PMID 24647631, 2014). "Furthermore, FOXC2 was upregulated in CSC-enriched populations and expression of FOXC2 in V12H-Ras-transformed HMLE cells was sufficient to drive EMT and increase their tumor forming and metastatic potential in transplants." (PMID 23986719, 2013). "As FOXC2 was only downregulated in GOT1 cells treated with CdML2T, TE may be affecting the secreted proteins of LX2 cells, which subsequently impairs the expression of this gene in the tumour cells." (PMID 40998421, 2025). "Among these genes are ERBB2, CCNA1, FOXC2, LEFTY2, VTN, ACKR3, and PTGS2, which influence processes such as apoptosis, epithelial–mesenchymal transition, angiogenesis, hypoxia responses, and KRAS signaling pathways, all vital for tumor aggressiveness and metastatic spread." (PMID 39000413, 2024). "These genes, including ERBB2, CCNA1, FOXC2, LEFTY2, VTN, ACKR3, and PTGS2, are involved in key processes like apoptosis, epithelial–mesenchymal transition, angiogenesis, response to hypoxia, and KRAS signaling pathways, which are crucial for tumor virulence and the spread of metastases." (PMID 39000413, 2024). "As in 4T1-T, endo-high cells within Axitinib treated tumors showed enrichment for FOXC2-targets, ECM, and hypoxia gene sets indicating that exposure to hypoxia in vivo through AAT promotes VM and the acquisition of an ECM-producing quasi-endothelial state in tumor cells." (PMID 37499655, 2023).
tumor (continued). "Thus, FOXC2 has emerged as an important transcriptional regulator of tumor cell-intrinsic and -extrinsic factors influencing EMT and angiogenic remodeling during tumor progression." (PMID 33889304, 2021). "It is unknown if FOXC2 plays a role in non-epithelial malignancies where EMT is not essential for tumor progression." (PMID 27634875, 2016). "Tumor FoxC2 expression is not restricted to the vasculature." (PMID 22174714, 2012). "Finally, the combined predictive significance of FOXC2 and other tumor markers was not assessed." (PMID 36425886, 2022). "We also report that FOXC2, a common denominator of multiple EMT pathways, plays a vital role in the acquisition of endothelial phenotypic and functional characteristics in vitro and in vivo, with the corollary that inhibition of FOXC2 signaling may compromise tumor neoangiogenesis." (PMID 33889304, 2021). "Given that the DANCR/miR-4707-3p/FOXC2 axis in ESCC, we hypothesize ZNF750 may directly downregulate DANCR expression, strengthened the interaction of miR-4707-3p with FOXC2-3′UTR in a ceRNA manner, leading to degradation of FOXC2 mRNA, thus playing tumor suppressive role in ESCC." (PMID 32341351, 2020). "Notably, tumor cells undergoing EMT acquire a migratory phenotype by ectopically expressing mesenchymal genes, including FoxC2, which first function in the developing embryo, and tumor cells may adopt many other developmental signaling pathways that function in their ancestral precursor cells." (PMID 22174714, 2012). "However, the upregulated methylation levels of FOXC2, FOXF1, FOXF2, FOXM1, and FOXN3 indicated that an epigenetic mechanism was not the main reason for the elevated FOX expression in tumor tissues." (PMID 36622275, 2023).
infection (3 papers, 2020 to 2024). The state of being infected such as from the introduction of a foreign agent such as serum, vaccine, antigenic substance or organism. "Our findings revealed that the levels of Gata2, Fat4 and Pkd1, which are related to cell polarization, as well as Egfl7, Nrp1 and Foxc2, which are related to valve development, were downregulated after infection." (PMID 38638427, 2024). "At the same time, infection itself does not activate EMT genes (or may even suppress HGF, FOXC2, and VEGFR genes) and is not able to induce an invasive phenotype formation." (PMID 32899940, 2020).
adenocarcinoma (2 papers, 2016 to 2017). A common cancer characterized by the presence of malignant glandular cells. "High FoxC2 expression was detected in 26.5 % of tumors, and significantly correlated with tobacco use (p = 0.047), adenocarcinoma (p = 0.008) and nodal involvement (p < 0.001)." (PMID 26758745, 2016). "A high level of FoxC2 expression was more frequently found in adenocarcinomas." (PMID 26758745, 2016). "Notably, high FoxC2 expression correlated with the histologic type of adenocarcinoma (p = 0.008)." (PMID 26758745, 2016). "The average fold-changefor FOXC2 and FOXQ1 expression levels ingastric adenocarcinoma samples was 3.076(P=0.045) and 2.622 (P=0.03) respectively." (PMID 28580309, 2017).
metabolic disorders (1 paper, 2025). "Deletion of the FOXC2 gene leads to impaired intestinal barrier, and dysregulation of intestinal microbiota and triggers metabolic disorders and systemic inflammation, which in turn exacerbates the onset and progression of T2DM." (PMID 41404514, 2025).
skeletal dysplasia (1 paper, 2021). Any Mendelian diseases that affects growth and development of the skeleton. "Loss of both Foxc1 and Foxc2 caused a general skeletal dysplasia predominantly affecting the vertebral column." (PMID 34331943, 2021). "Loss of Foxc1 and Foxc2 function in Col2-cre–expressing cells results in skeletal dysplasia and disrupts skeletal mineralization." (PMID 34331943, 2021).
FOXC2 also shares sentences with these, for which no sentence is quoted: Milroy disease (4 papers); alveolar capillary dysplasia (3); hypotrichosis (3); Tetralogy of Fallot (3); congenital heart defects (2); Ehlers-Danlos syndrome (2); Ewing sarcoma (2); glioma (2); hydrops (2); Telangiectasia (2); autosomal dominant disease (1); cervical cancer (1); cervical squamous cell carcinoma (1); cholangiocarcinoma (1); clear cell renal cell carcinomas (1); colon (1); congenital heart malformation (1); dyslipidemia (1); embryonal rhabdomyosarcoma (1); endometrial carcinoma (1); gastroenteropancreatic neuroendocrine tumors (1); head and neck squamous cell carcinoma (1); hematoma (1); Hydrocephalus (1); ischemic cardiomyopathy (1); larynx (1); late-onset lymphedema (1); leukaemia (1); lymphatic disorders (1); lymphatic malformation (1).
A further 21 diseases each share a sentence with FOXC2 in 1 paper.